RNU5F-7P (RNA, U5F small nuclear 7, pseudogene)
Gene: Small nuclear RNA gene on chromosome X (15,916,189 to 15,916,303, reverse strand). Ensembl gene ENSG00000200566.
Homologues: Orthologues: chimpanzee U5 (99% identical), macaque U5 (98% identical). Paralogues in human: RNU5F-3P (83% identical), RNU5E-7P (82% identical), RNU5E-4P (79% identical), RNU5F-6P (78% identical), RNU5F-8P (78% identical), RNU5A-4P (76% identical), RNU5A-7P (76% identical), RNU5A-3P (75% identical), RNU5E-10P (75% identical), RNU5B-4P (74% identical), RNU5E-8P (74% identical), RNU5A-6P (73% identical), and 13 more.